HMGA1P7 (high mobility group AT-hook 1 pseudogene 7)
Synonyms: formerly HMGA1L7
Gene: Transcribed processed pseudogene on chromosome 6 (134,115,235 to 134,115,736, reverse strand). Ensembl gene ENSG00000216753.
Diseases named in the same sentence as HMGA1P7 in open-access papers:
HMGA1P7 is named in the same sentence as 13 diseases in open-access papers, as found by Europe PMC text mining. Sharing a sentence is not in itself a finding about the gene and the disease. The quoted sentences say what the papers report.
breast adenocarcinoma (2 papers, 2014 to 2016). "As expected, we found upregulation of H19, IGF2 and HMGA1 following HMGA1P7 overexpression in MCF7 cells (human breast adenocarcinoma cell line)." (PMID 27874091, 2016).
breast carcinoma (2 papers, 2016 to 2022). "Lastly, the expression of HMGA1P7 was significantly correlated with H19 and IGF2 levels in human breast cancer thereby suggesting a role for HMGA1P7 deregulation in this neoplasia." (PMID 27874091, 2016). "HMGA1P6 and HMGA1P7, two pseudogenes of HMGA1 competing for endogenous RNA, can also lead to cancer when they are dysregulated, and the expression of HMGA1P7 is related to the levels of H19 and IGF2 in breast cancer, which is linked to the high double strand breaks in breast cancer cells." (PMID 35864955, 2022). "Altogether, these results strongly support the idea that HMGA1P7 could act as ceRNAs in human breast cancer and represent a novel potential mechanism accounting for H19 and IGF2 upregulation in these tumors." (PMID 27874091, 2016). "Then, we investigated whether HMGA1P7 functions as ceRNA through, or partially through H19, IGF2 and HMGA1 in breast cancer human cells." (PMID 27874091, 2016). "Finally, we show that expression of HMGA1P7 significantly correlates with H19 and IGF2 levels in human breast cancer, suggesting the upregulation of HMGA1P7 may increase H19 and IGF2 expression by a ceRNA mechanism then contributing to cancer progression." (PMID 27874091, 2016).
thyroid cancer (2 papers, 2014 to 2019). "Papillary (PTC) thyroid carcinomas, which are well differentiated and poorly aggressive, expressed low levels of HMGA1P6 and HMGA1P7." (PMID 25268743, 2014).
anaplastic thyroid carcinomas (1 paper, 2014). "HEK293 cells and 8505c cells (derived from a human anaplastic thyroid carcinoma) transfected with HMGA1P6- or HMGA1P7-expressing vectors grew significantly faster than the empty vector-transfected cells." (PMID 25268743, 2014). "Moreover, HMGA1P6 and HMGA1P7 were overexpressed in human anaplastic thyroid carcinomas, which are highly aggressive, but not in differentiated papillary carcinomas, which are less aggressive." (PMID 25268743, 2014).
B-cell lymphoma (1 paper, 2020). "For these mice FACS and immunohistochemical analyses suggested the diagnosis of B-cell lymphoma that was further supported by clonality analyses and RNA expression profile of the pathological tissues of the HMGA1P7 transgenic tissues." (PMID 32341372, 2020). "Taken together, these results indicate that HMGA1P7-TG mice lymphoid expansion was monoclonal, therefore further supporting the diagnosis of B-cell lymphoma." (PMID 32341372, 2020).
lymphoma (1 paper, 2020). A malignant (clonal) proliferation of B- lymphocytes or T- lymphocytes which involves the lymph nodes, bone marrow and/or extranodal sites. "Surprisingly, HMGA1 did not result upregulated by HMGA1P7 overexpression in the analysed pathological spleens, suggesting that pseudogene-induced lymphomas were based on other molecular targets already described." (PMID 32341372, 2020).
ovarian carcinoma (1 paper, 2019). A malignant neoplasm originating from the surface ovarian epithelium. "In agreement with our results, HMGA1P6 and HMGA1P7 expression was also upregulated in anaplastic thyroid and ovarian carcinomas and pituitary tumors, where it significantly correlates with HMGA1 overexpression." (PMID 31096664, 2019).
pituitary adenomas (1 paper, 2016). "Moreover, functional studies show that the enforced expression HMGA1P6 and HMGA1P7 enhances the proliferation of a pituitary adenoma cell line." (PMID 26895108, 2016). "Interestingly, HMGA1P6 and HMGA1P7 were also overexpressed in human pituitary adenomas where the HMGA proteins play a critical role in their development." (PMID 26895108, 2016). "In particular, HMGA1P6 and HMGA1P7 expression significantly correlates with HMGA1 mRNA in somatotropic and nonfunctioning pituitary adenomas." (PMID 26895108, 2016).
Splenomegaly (1 paper, 2020). Abnormal increased size of the spleen. "The analysis of HMGA1P7 transgenic mice at 12 months of age, shows that about 50% of these mice developed a pathology characterized by splenomegaly and invasion of lymphoid cells in different anatomical districts." (PMID 32341372, 2020). "Noteworthy, preliminary studies on a mouse strain overexpressing HMGA1P6 pseudogene show that several mice develop a lymphoid pathology characterized by splenomegaly that resembles that found in HMGA1P7-TG mice." (PMID 32341372, 2020). "About 50% of 12 months-old HMGA1P7 transgenic mice displayed splenomegaly at necropsy, whereas WT mice showed no relevant alteration in splenic size or weight." (PMID 32341372, 2020).
cancer (9 papers, 2014 to 2022). A tumor composed of atypical neoplastic, often pleomorphic cells that invade other tissues. "Altogether the data presented here show that deregulated expression of HMGA1P7 pseudogene has oncogenic role also in vivo, thus representing a new class of genes involved in cancer pathology as their upregulation occurs frequently in multiple human cancers." (PMID 32341372, 2020). "HMGA1 non-coding pseudogenes (HMGA1Ps), HMGA1P6 and HMGA1P7, are two processed pseudogenes that show conserved seed matches for miRNAs targeting the HMGA1 gene and other cancer-associated genes." (PMID 29149041, 2017). "In conclusion, the results described here reinforce the already known oncogenic role of the HMGA1P7 pseudogene as result of ceRNA mechanisms that enhance the expression of cancer-related genes." (PMID 29149041, 2017). "We have recently identified two pseudogenes, HMGA1P6 and HMGA1P7 for the HMGA1 gene whose overexpression has a critical role in cancer progression." (PMID 27874091, 2016). "Interestingly, HMGA1P6 and HMGA1P7 seem to affect cancer progression also by binding to the same miRNAs that target proteins involved in cancer progression." (PMID 25268743, 2014). "Interestingly, we found five upregulated cancer-related genes (Epha3, Hjurp, Kif26, S1pr3 and Pde3B) that shared miRNAs with the HMGA1P7 transcript." (PMID 25268743, 2014). "Consequently, it appears that HMGA1P6 and HMGA1P7 expression may contribute to cancer progression by acting as decoys for cancer-related genes other than HMGA1." (PMID 25268743, 2014). "We have recently identified and characterized two pseudogenes (HMGA1P6 and HMGA1P7) of the HMGA1 gene, which has a critical role in malignant cell transformation and cancer progression." (PMID 32341372, 2020). "This happens because of shared miRNAs targeting HMGA1P6, HMGA1P7, HMGA1 and other cancer related genes." (PMID 26895108, 2016). "Taken together, these results indicate that HMGA1P6, HMGA1P7 and HMGA1 expression is correlated with cancer aggressiveness." (PMID 25268743, 2014). "Interestingly, HMGA1P6 and HMGA1P7 also regulate the expression of EZH2, HMGA2, and other cancer-related genes with a critical role in cancer progression by sponging miRNAs able to target these genes." (PMID 35804851, 2022). "In conclusion, our finding that HMGA1P7-overexpressing MEFs grow faster and senesce later than their WT counterpart sustains our model in which HMGA1Ps act as ceRNAs that regulate HMGA1 and other genes by competing for shared miRNAs thus contributing to cancer progression." (PMID 25268743, 2014). "HMGA1P6 and HMGA1P7 are drastically upregulated in ATC but not in PTC, thus contributing to cancer progression." (PMID 35804851, 2022).
tumour (4 papers, 2014 to 2019). "Seventy transcripts that had a significant fold change variation (p <0.05) were examined as candidate genes involved in HMGA1P7 tumour-promoting activity." (PMID 25268743, 2014). "Similarly, for HMGA1P7, the augmentation in mRNA median expression values observed was of 3.19-, 9.79-, 8.82-, 10.94- and 6.28-fold in tumor stages IA, IB, II, III and IV, respectively, when compared with normal endometrial samples’ median expression value." (PMID 31096664, 2019). "Additionally, a significant increase in HMGA1P6 and HMGA1P7 expression was observed along tumor staging augmentation." (PMID 31096664, 2019).
HMGA1P7 also shares sentences with these, for which no sentence is quoted: papillary carcinoma (1 paper); pituitary tumor (1).